ICAM1 (intercellular adhesion molecule 1)
Diseases named in the same sentence as ICAM1 in open-access papers (continued):
Sharing a sentence is not in itself a finding about the gene and the disease.
COVID-19 (continued). "We found that Ang-2 (AUROC 0.75, best cutoff > 2800 pg-mL), RAGE (AUROC 0.69, best cutoff < 208 pg/mL), VCAM-1 (AUROC 0.74, best cutoff > 1312 ng/mL) and ICAM-1 (AUROC 0.63, best cutoff > 1092 ng/mL) were able to discriminate between COVID-19 and classical ARDS." (PMID 33608030, 2021). "In COVID-19-related acute respiratory distress syndrome, plasma ICAM-1 levels were found to be higher in non-survivors than in survivors." (PMID 34836309, 2021). "Our meta-analysis showed that expression of ICAM1 and PFKFB3 was increased in COVID-19 patients." (PMID 33520118, 2021). "ICAM-1 and thrombomodulin levels trended higher in patients with positive as compared to negative D-dimers, regardless of COVID-19 positivity." (PMID 34491250, 2021). "Furthermore, seven core targets of VA against COVID-19, including MAPK1, IL10, EGFR, ICAM1, MAPK14, CAT, and PRKCB were identified." (PMID 32805728, 2020). "Hence, the aim of our study was to evaluate and compare the profiles of endocan and other endothelial dysfunction biomarkers (ICAM-1, VCAM-1 and E-selectin) in hospitalized patients with different stages of COVID-19 severity, including critical COVID-19 on VV-ECMO patients." (PMID 39862311, 2025). "Our results demonstrate that COVID-19 driven cytotoxicity is cell selective not resulting in impaired endothelial cell viability but resulting in cellular activation and upregulation of ICAM-1 with subsequent immune cell adhesion and vWF deposition in the extracellular matrix." (PMID 38041432, 2024). "Regardless of clinical outcome, patients in our COVID-19 cohort showed limited differences in most serum inflammatory markers, although the mean or median values of several markers, such as TNFα, ICAM-1, CRP, AAT, and ferritin, were higher in more severe patients." (PMID 38494528, 2024). "The circulating ICAM1, which could originate from damaged endothelium, may contribute to prolonged inflammation even in recovered and no longer infectious COVID-19 patients, indicating the critical involvement of the endothelium in PASC." (PMID 39739157, 2024). "Furthermore, COVID-derived PBMCs and monocytes had upregulated expression of migration markers, including endothelial adhesion molecules, including L-selectin and intercellular adhesion molecule 1 (ICAM1), and CC/CXC chemokine receptors (CCR1, CXCR1), as a function of the severity of COVID-19." (PMID 37310504, 2023). "Furthermore, we found that some biomarkers of pulmonary endothelial injury, Ang-2 and ICAM-1, are significantly higher in non-survivors patients with COVID-19-related ARDS than in survivors." (PMID 33608030, 2021). "Therefore, the purpose of this study was to investigate serum ICAM-1 levels before and after debridement in patients with DFUs who were also diagnosed as COVID-19 positive compared with those who were COVID-19 negative." (PMID 33585030, 2021). "Therefore, this study aims to investigate the levels of ICAM-1 before and after debridement in patients with DFUs who are also diagnosed as COVID-19 positive compared with those who are COVID-19 negative." (PMID 33585030, 2021). "Besides, in silico models indicate that the mechanism of action of vitamin A against COVID-19 is carried out via modulation of gene expression of key proteins involved in inflammatory reaction and reactive oxygen species production (such as MAPKs, IL10, ICAM1, or PRKCB)." (PMID 35684054, 2022). "Adhesion molecules such as E-selectin, VCAM1 and ICAM1 are known to promote monocyte adhesion via integrin interaction, whereas an elevated PAI-1 level promotes thrombosis by inhibiting tPA, all of which may contribute to pro-inflammatory and pro-thrombotic conditions in patients with COVID-19." (PMID 34835015, 2021).
COVID-19 (continued). "Indeed, plasmatic level of vascular cell adhesion molecule-1 (VCAM-1), intercellular adhesion molecule 1 (ICAM-1), plasminogen activator inhibitor-1 (PAI-1), tissue factor (TF), and von Willebrand factor (vWF) antigens and activities are all elevated in severe COVID-19 cases." (PMID 35111777, 2021). "Notably, the plasma levels of adhesion molecules, such as ICAM-1, fractalkine, vascular cell adhesion molecule-1 (VCAM-1), vascular adhesion protein-1 (VAP-1), and vascular endothelial growth factor (VEGF), have been reported to be elevated among COVID-19 patients, especially in severe cases." (PMID 34578436, 2021). "Others, however, suggest that a year after discharge, patients who had contracted COVID-19 did not exhibit significant differences in serum IL-6, VCAM-1, ICAM-1 or P-selectin in comparison with matched sedentary healthy controls." (PMID 38600563, 2024). "In severe COVID-19 patients admitted to ICU (n = 38), increased levels of ICAM-1 and E-selectin, but not VCAM-1 or P-selectin, were found in COVID-19 patients who died during hospitalization (n = 10), compared to survivors (n = 28)." (PMID 36941580, 2023). "The most severe forms of COVID-19 ARDS are characterized by the predominance of “endothelial” injury over “alveolar” injury, as evidenced by higher levels of Ang-2 and ICAM-1 in non-survivors compared to survivors." (PMID 34360707, 2021). "Endothelial activation was absent in renal tissue from COVID-19 patients as indicated by the lack of E-selectin, VCAM-1 and ICAM-1 upregulation." (PMID 34112226, 2021). "We found that the plasma levels of Ang-2 and ICAM-1 at T1 were higher in non-survivors than in survivors and, furthermore, i.e., that the plasma levels of Ang-2 and ICAM-1 increased rapidly in COVID-19 non-survivors, within 24 h from ICU admission." (PMID 33608030, 2021). "When comparing only patient groups in the first week of hospitalization, s-ICAM-1 and s-VCAM-1 values did not significantly differ between patient groups, although s-VCAM-1 values tended to be lower in patients with critical COVID-19 on VV-ECMO (P = 0.053 vs. severe, at admission)." (PMID 39862311, 2025). "Moreover, cell adhesion markers such as ICAM1, PECAM1, and SELE were markedly, and significantly, upregulated in COVID-19, influenza, and non-influenza viral myocarditis (FDR < 0.001)." (PMID 36371548, 2023). "MMP-1 enzymatic activity and multiple EC activation markers (soluble forms of CD146, intercellular adhesion molecule 1 (ICAM-1), and vascular cell adhesion molecule 1) were found to be significantly elevated in ICU patients, compared to non-ICU patients with COVID-19." (PMID 37199573, 2023). "As for ICAM-1, the pathways and even ICAM-1 are absent in the current COVID-19 Disease Map." (PMID 37719701, 2023). "However, signaling pathways that consist of ICAM-1 and other molecules interacting with ICAM-1 are not identified in COVID-19." (PMID 37719701, 2023). "The aim of this study was to evaluate whether the plasma levels of “endothelial” and “alveolar” biomarkers (Ang-2, ICAM-1, VCAM-1, P selectin, E-selectin and RAGE) vary over time between survivors and non-survivors in COVID-19-related ARDS patients." (PMID 33608030, 2021).
Stroke (121 papers, 2008 to 2026). Sudden impairment of blood flow to a part of the brain due to occlusion or rupture of an artery to the brain. "ICAM‐1 has been strongly implicated in the neutrophil‐mediated inflammatory response associated with stroke, both in ischemia and ICH." (PMID 41498036, 2025). "Soluble ICAM‐1 levels are elevated in patients with ischemic stroke and are associated with stroke outcome." (PMID 37452512, 2023). "A multivariate analysis has shown that sICAM-1 (soluble intercellular adhesion molecule 1) serum levels on admission are associated with neurological deterioration in stroke patients." (PMID 37342100, 2023). "In experimental stroke, infarct size and brain leukocyte infiltration have been found to be decreased in adhesion molecule deficient animals when ICAM-1 was blocked." (PMID 36793730, 2023). "Together, these results suggest that the beneficial effects of dBET1 in stroke are associated, in part, with reduced ICAM-1 levels." (PMID 35761277, 2022). "Plasma lipid peroxides concentration was positively related to ICAM-1 and presence of stroke, whereas platelet lipid peroxides were positively associated with vWF." (PMID 35739962, 2022). "Transcriptional analysis confirmed a reduction in expression of co-stimulatory genes in the spleen known to be expressed by macrophages 1–5 days after experimental stroke including Cd40, Cd80, Cd86, Icam1, Tnfsf9, which encodes 4-1BBL, and Cd274." (PMID 29872438, 2018). "ICAM-1 has been implicated in stroke pathophysiology and offers an effective therapeutic target for reduction of ischemic lesion development." (PMID 28509283, 2017). "Allopurinol use was associated with attenuation of intercellular adhesion molecule-1 levels in patients after a recent stroke." (PMID 27604082, 2016). "The association between well-water As and stroke was significantly modified by 11 SNPs in six genes, and ICAM1 rs281432 remained significant after FDR adjustment (padj = 0.014)." (PMID 25575156, 2015). "Increase of ICAM-1 is linked to stroke-related neurological deterioration, and poor short-term stroke prognosis." (PMID 21871109, 2011). "Studies show that ICAM-1 deficiency in mice models ameliorates stroke." (PMID 40362673, 2025). "The community‐based Austrian Stroke Prevention Study found that ICAM‐1 was associated with age‐ and gender‐adjusted WMH lesion progression at both 3 and 6 years (3‐year OR, 1.007; 95% CI, 1.002–1.012; p = 0.004; and 6‐year OR, 1.004; 95% CI, 1.000–1.009 per ng/ml; p = 0.057)." (PMID 36478511, 2023). "In multivariable analysis, lipid peroxides are associated with ICAM-1 and a history of stroke." (PMID 35739962, 2022). "Many of these effects including improvement of endothelial function and reduction of oxidative stress, reduction of glycosylated hemoglobin, and attenuation of intercellular adhesion molecule-1 levels, may potentially lower the risk of stroke." (PMID 27604082, 2016). "Thus, the delivery of a murine monoclonal antibody directed against intercellular adhesion molecule-1 (ICAM1) within 6 hours of symptom onset aggravated neurological recovery assessed by the mRS score, increased stroke mortality and increased infection susceptibility." (PMID 35087539, 2021). "Endothelial β2-integrin ligand ICAM-1 has an impact on neutrophil recruitment in stroke through the BBB." (PMID 40362673, 2025). "During stroke, ICAM‐1 expression is upregulated, facilitating the adhesion and transmigration of neutrophils and other immune cells into the brain parenchyma, which aggravates inflammation and contributes to the extent of ischemic or hemorrhagic injury." (PMID 41498036, 2025). "One study highlights that elevated levels of soluble intercellular adhesion molecule-1 (sICAM-1) are related to sleep fragmentation after stroke rehabilitation, serving as an inflammatory marker that links functional improvement from stroke to sleep quality." (PMID 40136392, 2025).
Stroke (continued). "Nevertheless, one study showed higher ICAM-1 levels in AIS patients who suffered more severe strokes measured by NIHSS." (PMID 39091977, 2024). "In Italian patients, an increased risk of stroke was found in carriers of both the IL6–174GG and ICAM1 469E/E genotypes of the IL6–174 G > C (rs1800795) and ICAM1 469 E > K (rs5498) polymorphisms." (PMID 38638292, 2024). "Within a few hours after a stroke, ICAM-1 expression rises in the proximal endothelial tissue of the brain damage, peaking at around 12–48 hours." (PMID 36793730, 2023). "The blocking of IL-1 receptor, L-selectin, or ICAM-1 has been shown to reduce ischemic injury via reduction of neutrophil-platelet aggregates in preclinical stroke models." (PMID 37117163, 2023). "In humans, elevated levels of VCAM-1 and ICAM-1 are found in the blood and in the infarcted areas of stroke patients." (PMID 36745280, 2023). "Since the list of pro-inflammatory cytokines is vast, we selected ICAM-1 and several other genes that were previously identified in either stroke, cardiovascular disease, or other artery related diseases." (PMID 37158955, 2023). "Real-time PCR analysis in rats after t-MCAO has revealed that the mRNA levels for TNF-a, IL-1b, IL-6, E-selectin, and ICAM-1 are increased 3 h after stroke that persist for 24 h in the hemisphere ipsilateral to occlusion." (PMID 37342100, 2023). "Stroke resulted in upregulated expression of adhesion molecules (P‐selectin, E‐selectin, and ICAM‐1) and chemokines (CC‐chemokine ligand (CCL)‐2, CCL‐3, CCL‐4, CCL‐5, and chemokine C‐X‐C ligand 1 (CXCL‐1))." (PMID 37122157, 2023). "Post-ischemic dBET1 treatment significantly reduced MMP-9 levels, neutrophil infiltration into the ischemic brain, and dysregulated levels of cellular adhesion molecules (e.g., ICAM-1) after stroke." (PMID 35761277, 2022). "Intercellular adhesion molecule 1 (ICAM-1) is known to exacerbate BBB permeability during stroke and play a significant role in the cascade of immune cell transmigration into the brain parenchyma." (PMID 35761277, 2022). "Real-time quantitative PCR and Western blot analyses showed that stroke led to a marked upregulation of ICAM-1 mRNA and protein levels, which were significantly attenuated by dBET1 treatment." (PMID 35761277, 2022). "After a stroke, adhesion molecules (e.g., ICAM-1) mediated several leukocytes and cytokines (e.g., VEGF and IL-7) entered into the brain through the injured blood-brain barrier." (PMID 35720096, 2022). "IL1B, IL10, TNF, IL6, and ICAM1 are closely related to the inflammatory response after stroke, among which IL-10 is an important anti-inflammatory factor, while L1B, TNF, and IL6 are proinflammatory factors." (PMID 33727944, 2021). "Larger strokes have been shown to be associated with lower levels of TNF-α, IL-1β, P-selectin, and ICAM-1 as compared to lacunar strokes." (PMID 35008440, 2021). "The blockade of ICAM-1 with specific antibodies also reduced infarction and leukocyte infiltration of brain tissues in rats and rabbits following experimental stroke." (PMID 34868060, 2021). "In humans after stroke, enlimomab, an ICAM‐1 antibody, induces worse recovery, fewer symptom‐free patients, more infections, and fever." (PMID 34693660, 2021). "Clinical tests showed an increase in ICAM-1 concentration in the blood serum and cerebrospinal fluid of patients after stroke." (PMID 34868060, 2021). "Neuroprotective effects of humanized antibodies against the NMDA receptor, intercellular adhesion molecule-1 (ICAM-1), and E-selectin have been demonstrated in pre-clinical stroke models." (PMID 32872405, 2020). "A study showed that knockdown of intercellular adhesion molecule-1 (ICAM-1) gene in mice reduced the infarction of the brain, suggesting that inflammation response plays a major role in pathogenesis of stroke." (PMID 33066616, 2020).
Stroke (continued). "In the current study, the Pearson analyses showed that the serum levels of three CAMs (E-selectin, VCAM-1, and ICAM-1) were all positively correlated with infarct volume at 48 h after stroke onset in CIS patients." (PMID 32264912, 2020). "Brain endothelial cells are activated by IL-1 after stroke via binding of IL-1R1, leading to the upregulation of ICAM-1, VCAM-1 and P-Selectin expression, as well as various chemokines, resulting in neutrophil adhesion and infiltration." (PMID 30453020, 2019). "When comparing the baseline values from the included stroke patients to values from healthy individuals (manufacturer's normative values), the levels of inflammatory, cardiovascular biomarkers and ICAM-1 were generally higher in the stroke patients." (PMID 31316451, 2019). "The expression of such proteins, including vascular cell adhesion molecule-1 (VCAM-1) and intracellular adhesion molecule-1 (ICAM-1), is upregulated post-stroke." (PMID 31281252, 2019). "The ICAM-1 levels are increased after stroke in both animals and patients, and blocking ICAM-1using antibodies reduces ischemic damages after transient MCAO in rats." (PMID 30971272, 2019). "This study aimed to determine the diagnostic potential of ICAM-1-targeted MPIO for in vivo MRI of vascular ICAM-1 expression and leukocyte infiltration at different stages after stroke in mice." (PMID 28509283, 2017). "Immunohistochemistry on postmortem brain tissue showed that the αICAM-1-MPIO accumulation at these subacute post-stroke stages was confined to ICAM-1-positive vessel-like structures, and occasionally co-localized with vessel-restricted leukocytes." (PMID 28509283, 2017). "We have recently developed an optimized molecular MRI approach for the detection of stroke-induced expression of intercellular adhesion molecule-1 (ICAM-1)." (PMID 28509283, 2017). "αICAM-1-MPIO are suitable for in vivo MRI of ICAM-1 expression on vascular endothelium and leukocytes at different stages after stroke." (PMID 28509283, 2017). "ICAM-1 expression is an essential step in mediating the firm adhesion of leukocytes in cerebral microvessels after ischemic stroke, and there are several studies that address the contribution of ICAM-1 to cerebral injury after stroke." (PMID 28115020, 2017). "Stroke also resulted in an inflammatory response in the fat of obese mice characterised by increased IL-6, TNFα and ICAM-1 expression." (PMID 28798136, 2017). "ADFm overexpression in ECs reduced the expression of 11 markers, including CCL2 and ICAM-1, which are known to facilitate macrophage and neutrophil infiltration after stroke." (PMID 26813496, 2016). "In experimental stroke models, blocking ICAM-1 reduced infarct volume, decreased mortality, and improved outcomes via pharmaceutical intervention and genetic deletion, as well as immunodepletion of neutrophils volume." (PMID 27688603, 2016). "Our recent data indicate that Ex-4 treatment reduces stroke-induced frontal cortex edema, endoplasmic reticulum stress, apoptosis, and upregulation of aquaporin 4, glial fibrillary acid protein, and ICAM-1." (PMID 27296974, 2016). "The fact that leukocytes also express functionally relevant ICAM-1 provides novel approaches to interpret findings from stroke studies using ICAM-1 antibodies or ICAM-1 knock-out animals." (PMID 26640428, 2015). "ICAM-1 also contributes to brain leukocyte accumulation and leukocyte-mediated tissue injury in experimental models of stroke, meningitis, and systemic trauma." (PMID 25013810, 2014). "In animal models, the over-expression of ICAM1 has been related to enhanced leukocyte adherence and persistent activation in post-injury cerebral ischemia where its increase can contribute to stroke severity." (PMID 23874624, 2013). "Chronic increase in IL-1β expression in the brain led to leukocyte infiltration and increased MCP-1 and ICAM-1 expressions in a mouse model, which is a phenotype also seen in stroke lesions." (PMID 23326018, 2012).